Y_RNA (Y RNA )
Gene: Miscellaneous RNA gene on chromosome 9 (109,042,386 to 109,042,487, reverse strand). Ensembl gene ENSG00000199331.
Homologues: Orthologues: chimpanzee Y_RNA (98% identical), macaque Y_RNA (95% identical). Paralogues in human: Y_RNA (84% identical), Y_RNA (83% identical), RNY3 (82% identical), Y_RNA (82% identical), RNY3P14 (81% identical), Y_RNA (81% identical), Y_RNA (80% identical), RNY3P1 (79% identical), Y_RNA (79% identical), RNY3P2 (78% identical), Y_RNA (78% identical), RNY3P11 (77% identical), and 93 more.